MIR937 (microRNA 937)
Synonyms: hsa-mir-937; MIRN937; mir-937
Gene: MicroRNA gene on chromosome 8 (143,812,957 to 143,813,042, reverse strand). Ensembl gene ENSG00000284224.
Gene Ontology:
Biological process: miRNA-mediated post-transcriptional gene silencing